NRAS (NRAS proto-oncogene, GTPase)
Diseases named in the same sentence as NRAS in open-access papers (continued):
Sharing a sentence is not in itself a finding about the gene and the disease.
melanoma (continued). "Melanomas arise from melanocytes in which mutations typically target the proteins of the mitogen-activated protein kinase (MAPK) signalling pathway: BRAF (viral RAF murine sarcoma viral oncogene homolog B1) and NRAS (neuroblastoma RAS viral oncogene homolog)." (PMID 32796736, 2020). "Additionally, NRAS upregulation was verified in melanoma samples, when compared to normal skin tissues." (PMID 33072757, 2020). "The same study shows that NRAS+ nor BRAF+ was associated with overall melanoma-specific survival, but the risk of death was significantly more reduced for higher-risk NRAS+ or BRAF+ (T2 or higher stage)." (PMID 32637031, 2020). "No concomitant mutation in BRAF and NRAS genes was detected, further confirming that deleterious mutations in these driver oncogenes are mutually exclusive in melanoma." (PMID 32751423, 2020). "Furthermore, BRAF and NRAS mutations are mutually exclusive, as well as TERT C250T and C228T, and then, a maximum of two mutations will be tested in plasma for each melanoma patients, making feasible the dPCR approach proposed in this study." (PMID 33122747, 2020). "Even though solar ultraviolet exposure is the main environmental risk factor for cutaneous melanoma development, there are still genetic susceptibility factors, such as germline mutations in p16 or CDK4, and genesis of melanoma, such as the main genetic drivers BRAF, NF1 and NRAS mutations." (PMID 32333246, 2020). "Thus, based on these observations, we demonstrate that combining trametinib with takinib, a TAK1 inhibitor is a far more efficient treatment than monotreatment with trametinib in NRAS‐mutant melanoma cells." (PMID 31549767, 2020). "BRAF, NRAS and TERT mutations occur in more than 2/3 of melanomas." (PMID 33122747, 2020). "This analysis revealed a heterozygous NRAS Q61K (c.181C > A, rs1219132549) mutation, which is a well-known oncogenic variant in melanomas and thyroid carcinomas that has not been described in PPGLs previously." (PMID 33138083, 2020). "We used three different cell lines with frequent gene mutations in melanoma (BRAF, NRAS, or cKIT)." (PMID 32455924, 2020). "Moreover, nelfinavir is effective in BRAF and NRAS mutant melanoma cells isolated from patients progressed on MAPK inhibitor therapy and in BRAF/NRAS/PTEN mutant tumors." (PMID 33322354, 2020). "Moreover, we demonstrate that combining the MEK inhibitor trametinib with the TAK1 inhibitor, takinib achieves far greater efficacy than treatment with trametinib alone in NRAS‐mutant melanoma cells." (PMID 31549767, 2020). "The Cancer Genome Atlas Network has recently provided a potential step ahead in the comprehension of melanoma genesis, proposing a classification of melanoma based on protein, RNA and DNA analysis from over 300 melanoma patients, in addition to BRAF, NRAS, and NF1 mutational profile." (PMID 33233603, 2020). "To determine whether the use of our system can be extended to the analysis of multiple loci, we designed a sgRNA library for three genes (MAP2K1, KRAS, and NRAS) related to vemurafenib resistance in melanoma." (PMID 32242071, 2020). "The frequency of mutations in the genes is consistent with that reported in the literature for IDH1 and IDH2 in brain tumors, EGFR and KRAS in NSCLCs, KRAS and NRAS in CRCs, BRAF, RAS, PIK3CA, and TERT in thyroid nodules, BRAF, NRAS and cKIT in melanoma, and KRAS in pancreatic pre-operative samples." (PMID 32340363, 2020). "Mutations of BRAF, NRAS, and KIT genes have been correlated to the development of melanoma." (PMID 31274706, 2020). "Detectable ctDNA before complete surgical resection in patients with AJCC stage IIIB/C/D (high-risk stage III) with a BRAF, NRAS, or KIT mutant melanoma is an independent predictor of worse melanoma-specific survival (MSS) in patients receiving no systemic adjuvant therapy." (PMID 33233603, 2020). "Oncogenic BRAF and NRAS mutations are the most common melanoma driver mutations, yet these mutations typically do not match the UV signature." (PMID 33207206, 2020).
melanoma (continued). "Interestingly, intra-patient heterogeneity of BRAF and NRAS molecular alterations between paired primary melanoma and metastasis has been described with observed discordance rate 13,3%." (PMID 33100226, 2020). "Indeed, oncogenic NRAS is involved in heightened migration in melanoma cell lines and inhibition of NRAS by microRNAs was successful in reducing trans-well migration." (PMID 32660441, 2020). "Although these are among the most recurrent mutations in melanoma and are associated with carcinogenesis, neither is a canonical UV signature mutation: NRAS Q61R is caused by a T>C mutation, while BRAF V600E is caused by a T>A mutation in a non-Dipyr context." (PMID 33207206, 2020). "In addition, the melanoma oncogenes BRAF or NRAS, as well as hypoxia, nutrient deprivation, or immune mediators are common stress triggers during melanoma development and maintenance." (PMID 32978520, 2020). "In vitro and in vivo studies revealed that SR4 and niclosamide, two small molecules mitochondria uncouplers, can be used successfully in the treatment of naïve wild type, BRAFV600E and NRAS mutants, vemurafenib-resistant melanomas and melanomas with greater OXPHOS phenotype." (PMID 32528879, 2020). "This is especially true for patients who show no benefit after standard of care, become resistant or belong to somatic mutation subgroups for which no targeted therapy option exists, such as BRAF wild-type melanomas including NRAS mutant and NF1 loss-of-function melanomas." (PMID 33260923, 2020). "Additionally, mutations were common in melanoma, including BRAF (50%), NRAS (30%), MAP2K1 (6%), and KIT (2.6%)." (PMID 33133157, 2020). "In melanoma, 46% of the detected variants were found in BRAF and 15% in NRAS genes." (PMID 33083132, 2020). "As RNA amounts extracted from EVs are limiting, the miRNomes of nEVs and hEVs were analysed by highly sensitive qPCR arrays for a BRAF mutant (A375) and for an NRAS mutant melanoma cell line (MelJuso), while analysis of the miRNomes of WCLs was performed by miRNA microarrays." (PMID 32183388, 2020). "Zebrafish BRAF and NRAS-dependent melanomas do not display the same frequencies of mutations as seen in sun-exposed human melanoma." (PMID 32455885, 2020). "More importantly, the associations explored in detail in this study such as the essentiality of SRF in skin and dependence of NRAS‐mutant melanoma on IGF1R and FURIN hold true in the integrated data set and with even higher confidence suggesting that these are indeed robust associations." (PMID 33073517, 2020). "Each of these variants of uncertain significance occurred in BRAF, NRAS, or NF1 mutant melanomas." (PMID 32483240, 2020). "NRAS Q61R is a known driver frequently found in human melanoma, angiosarcoma and other cancers." (PMID 32210430, 2020). "Interestingly, NRAS-mutant melanoma patients show worse survival, relapse rate and therapy response than patients with wild type NRAS or with BRAF mutations." (PMID 31906480, 2020). "Interestingly, higher concentrations of SB590885 also negatively affected the growth of NRAS-mutated cell lines, indicating the possibility of additional, BRAF-independent, cytotoxic activity of the pyridinyl imidazole compounds in melanoma cells." (PMID 32531927, 2020). "In melanoma, TPMs have been shown to associate with poor disease-free and melanoma-specific survival and if simultaneously present with BRAF/NRAS oncogenic mutations, it could predict worst disease-free progression and melanoma-specific survival." (PMID 32674474, 2020). "Others have reported, however, that overall survival is not different between WT and NRAS-mutated melanomas." (PMID 32429485, 2020).
melanoma (continued). "The inhibitory effect of SB202190 on ERK activity was observed in human melanoma cell lines carrying BRAF V600E mutation (A375, G361, Colo-800), but not in melanoma cells with NRAS mutations (MEL-JUSO, SK-MEL-30, IPC-298)." (PMID 32531927, 2020). "Similarly, XL888 suppressed ERK1/2 activity in NRAS-mutant melanoma cell lines exposed to vemurafenib, and this effect was associated with down-regulation of CRAF." (PMID 31659567, 2020). "Interestingly, MEK inhibitors have demonstrated a modest improvement in the PFS of NRAS-mutant melanoma patients even when compared with chemotherapy with dacarbazine." (PMID 33072757, 2020). "Here, we lowered the oxygen concentration applied to melanoma cells to 1% and isolated EVs of four melanoma cell lines (two carrying the BRAF V600E mutation (A375, 501Mel) and two carrying an NRAS mutation (MelJuso, IPC298)); control cells were kept under normoxic conditions." (PMID 32183388, 2020). "We proposed to standardize a liquid biopsy platform to identify hotspot mutations in BRAF, NRAS and TERT in plasma samples from advanced melanoma patients and investigate whether it was associated to clinical outcome." (PMID 33122747, 2020). "Typically, 15–20% of malignant melanomas possess NRAS gene mutations, but no cases of NRAS-mutated PML have been reported in the English literature." (PMID 32028967, 2020). "In addition, we demonstrate that combining trametinib with the TAK1 inhibitor, takinib, is a far more efficient treatment than trametinib alone in NRAS‐mutant melanoma cells." (PMID 31549767, 2020). "IRS-1 remained significantly higher in NRAS mutant vs BRAF mutant melanomas at the protein level." (PMID 33082316, 2020). "The CSD melanomas often have additional KIT, NRAS and NF1 mutations." (PMID 32283832, 2020). "The genes with the most frequent mutations in melanoma are BRAF and NRAS." (PMID 32775409, 2020). "To elucidate whether the tumor suppressive roles of FUT8-AS1 in melanoma were dependent on the regulation of miR-145-5p/NRAS/MAPK signaling axis, we inhibited miR-145-5p in FUT8-AS1 overexpressed CHL-1 cells." (PMID 34094894, 2020). "Moreover, Dinter and collaborators have suggested a potential role of the combination of MEK and BRAF inhibitors, due to the increased levels of endoplasmic reticulum stress detected in NRAS-mutant melanoma cell lines." (PMID 32825562, 2020). "For this reason, the aim of revising all studies evaluating the frequency of mutations of BRAF, NRAS, and KIT genes are to determine the correlation of the clinical-pathological characteristics of melanomas, and the demographic characteristics of the analysed populations." (PMID 31274706, 2020). "In addition, studies have shown that BRAF and NRAS mutant melanomas have similar metastasis rates and they are slightly more likely to metastasize than BRAF and NRAS wild-type melanomas." (PMID 32894090, 2020). "Additionally, we observed higher sAXL levels in patients with NRAS mutation compared to NRAS wild type (p value = 0.0143), conferring with a previous report showing higher AXL cellular levels in NRAS mutated melanoma cell lines." (PMID 31917795, 2020). "The melanoma panel consistently detected both NRAS mutations at 1.3% and 0.26% frequency but did not accurately detect the NRAS mutations at 0.13% MAF." (PMID 32785074, 2020). "To further assess the involvement of the TAK1 signaling pathway in trametinib resistance in NRAS mutant FBXO42 KO melanoma cells, we combined trametinib with takinib, the potent and selective TAK1 inhibitor, and tested their inhibition of FBXO42 KO cell growth." (PMID 31549767, 2020). "Melanomas with NF1 mutations typically occur on chronically sun-exposed skin or in older individuals, show a high mutation burden, and are wild-type for BRAF and NRAS." (PMID 32393282, 2020).
melanoma (continued). "Concerning ctDNA molecular features, mutations in the BRAF, NRAS, KIT and TERT genes are considered melanoma-driving mutations and their detection could help to adapt the strategy for patient monitoring." (PMID 32295074, 2020). "The progression from a premalignant lesion to melanoma is accompanied by an increase in the number of mutations in the MAPK pathway; in this study, 76% of invasive melanomas presented mutations in the BRAF gene, and 28% (7/25) presented mutations in both the BRAF gene and the NRAS gene." (PMID 32775409, 2020). "NRAS and BRAF mutations are usually mutually exclusive in melanoma." (PMID 32054078, 2020). "In melanoma cells, the altered signaling pathways in SK-MEL-147 cells, which have an NRAS mutation and 501Mel cells, which have a BRAF mutation, could also be a reason for the differential response to BET inhibitors." (PMID 32151278, 2020). "Up to 70% of melanomas exhibit activating mutations within the kinases BRAF gene and approximately 15% of melanomas within NRAS gene, resulting in constitutive and sustained activation of downstream targets, RAS–MEK–ERK1/2 axis, in addition to unresponsive negative feedback mechanisms." (PMID 33212834, 2020). "In another study of 127 melanomas, eight had MAP2K1 point mutations and two had MAP2K2 point mutations; these alterations were associated with constitutive ERK phosphorylation, and most co-occurred with either BRAF or NRAS mutation." (PMID 32483240, 2020). "Similarly, in another recent work, researchers compared ddPCR with Sanger sequencing and pyrosequencing in 40 melanoma FFPE tissues regarding the detection rates of mutations in BRAF, NRAS, and TERT promoter." (PMID 32695793, 2020). "INO80 has been reported to promote growth of NRAS oncogene mutant-driven melanoma cells." (PMID 32913330, 2020). "In addition to IGF1R itself, gene encoding the FURIN protease, which is required for surface presentation of IGF1R, also had a higher essentiality in NRAS‐mutant melanoma cell lines compared cells with WT NRAS." (PMID 33073517, 2020). "The melanoma patients were first classified according to the status of BRAF and NRAS mutation." (PMID 32411243, 2020). "In contrast, CDKN2A promoter hypermethylation occurs most frequently in NRAS-mutant melanoma (87.7%) and is less common in melanoma with BRAF mutations (67.0% with CDKN2A promoter methylation) and in melanomas with NF1 mutations (77.3% showing CDKN2A promoter methylation)." (PMID 33076392, 2020). "This custom ddPCR panel would have a predicted coverage of ~80% of cutaneous melanomas based on the skin cutaneous melanoma TCGA dataset which gives a BRAF/NRAS coverage of ~70% and the fact that TERT promoter mutations are found in around ~29% of BRAF wild-type melanoma patients." (PMID 32785074, 2020). "For the more aggressive NRAS-mutated melanomas, however, there are no specifically targeted therapies available; thus, a significant unmet need remains for new treatment options." (PMID 32610581, 2020). "However, we observed a significant higher ST8SIA1 expression in melanoma patients with BRAF V600e mutation compared to those that were triple WT (wild type of BRAF, NRAS, and NF1 mutations) or NRAS mutation(s) alone." (PMID 32358995, 2020). "While only melanoma cells bearing the BRAF V600E mutation responded in our assays to pyridinyl imidazole compounds by ERK signaling inhibition, the cellular vacuolization, and delocalization of mTOR kinase was observed in both NRAS- and BRAF-mutant cells." (PMID 32531927, 2020). "Overall, our custom sequencing panel targeting commonly mutated genes in melanoma was effective in providing mutational information in most patients, allowing for identification of targetable mutations for ctDNA analyses in patients WT for BRAF and NRAS." (PMID 30312528, 2019).
melanoma (continued). "Furthermore, positive phase III data have been reported for the NEMO study comparing the efficacy of binimetinib single agent versus dacarbazine in unresectable or metastatic NRAS-mutant melanoma." (PMID 30956763, 2019). "Dysregulated phosphorylation of NRAS at S89 activates and promotes melanoma genesis." (PMID 31480283, 2019). "Sixty five consecutive formalin-fixed paraffin-embedded (FFPE) melanoma samples were prospectively tested for BRAF mutations with the VE1 (anti-BRAF V600E) antibody and for both BRAF and NRAS mutations with the Idylla NRAS-BRAF-EGFR S492R Mutation Assay cartridges." (PMID 31415669, 2019). "A similar response was observed in seven additional melanoma cell lines regardless of the presence or absence of BRAF or NRAS oncogenic mutations." (PMID 31040916, 2019). "Thus, AZD5991 can delay acquired resistance to BRAFi or MEKi in BRAF-mutant or NRAS-mutant melanoma cells." (PMID 31727888, 2019). "In this study BRAF, NRAS, KRAS, HRAS, PIK3CA and KIT mutations were examined in melanomas." (PMID 31277584, 2019). "Volasertib (BI 6727) had been shown to delay growth of melanoma tumors and to cause regression by inducing apoptosis in vivo and, importantly, it showed synergistic antitumor effects together with the MEK inhibitor Trametinib in NRAS mutant melanoma." (PMID 30728057, 2019). "The presence of BRAF or NRAS mutations does not confer an increased risk of malignant transformation, and further mutations are required to cause melanoma formation in a CMN." (PMID 30782194, 2019). "Similarly to NRAS, BRAF mutations suggest the existence of genotoxic agents in mucosal melanoma, which remain to be identified." (PMID 31398831, 2019). "The selection of mutational targets for ctDNA analysis was based on the following criteria: (a) known melanoma hotspot mutation in BRAF, NRAS, and/or TERT promoter; (b) COSMIC/TCGA reported mutation; (c) other mutation with a polyPhen score >0.7 and high variant allele frequency (VAF) in the tumor." (PMID 30312528, 2019). "However, so far, only one mucosal melanoma carrying both mutants (BRAF D594E + NRAS G13R) has been described." (PMID 31398831, 2019). "ARAF might also be a therapeutic target in NRAS-mutated melanoma, as it was recently established that ARAF could mediate MAPK pathway activation under specific conditions in melanoma." (PMID 31398831, 2019). "Thus, we reviewed the BRAF or NRAS mutation status in TCGA-SKCM dataset, and our results showed the prognostic values of the 7-lncRNA signature in melanoma patients with different subtypes." (PMID 31649871, 2019). "In addition, there is a well-known repertoire of common driver mutations in melanoma, with the most prevalent being mutations in BRAF, NRAS." (PMID 31649871, 2019). "Although BRAF and NRAS are frequently mutated in human melanoma, coexistence of BRAF c.1799T>A(V600E) and NRAS c.181C>A (Q61K)/182A>G (Q61R) changes within the same melanoma tumor is essentially nonexistent except in situations of acquired resistance to BRAF inhibitors." (PMID 30651601, 2019). "Additionally, combinatorial treatment of low‐dose magnolol and targeted therapy or chemotherapy led to an increase in cell death in BRAF‐ and NRAS‐mutant melanoma cells demonstrating a synergistic effect." (PMID 30793515, 2019). "In other tumor types, such as melanoma, colorectal, and lung cancer, activating BRAF mutations occur mostly in a non-overlapping distribution with other genes that converge on activation of ERK signaling pathways (i.e., KRAS, NRAS, NF1, EGFR)." (PMID 31158244, 2019). "The rationale for these groupings is that genes with parallel or related functions relevant to melanoma may harbor mutually exclusive mutations, as is the case for BRAF and NRAS, such that they would escape notice when examined individually." (PMID 30956763, 2019). "Melanoma cells with oncogenic NRAS were the least sensitive (IC50 above 400 nM)." (PMID 31040916, 2019).